CXCR4 (C-X-C motif chemokine receptor 4)
Diseases named in the same sentence as CXCR4 in open-access papers (continued):
Sharing a sentence is not in itself a finding about the gene and the disease.
glioma (continued). "Although AurA and CXCR4 are also increased in GBM tumors compared to astrocytomas and oligodendrogliomas, the correlation between AurA/CXCR4 expression and the grade of glioma malignancy remain to be proved." (PMID 30082913, 2019). "In particular, it has been demonstrated that upregulation of MIF in glial tumour cells is induced by hypoxic and hypoglycaemic stress and that MIF and CXCR4 colocalize in hypoxic area in glioma specimens." (PMID 29707160, 2018). "In particular, CXCR4 on GBM cells and SDF-1 produced by endothelial cells direct perivascular invasion as demonstrated in vitro and in orthotopic glioma mouse models." (PMID 30622535, 2018). "It is plausible that gp120 binding to CXCR4 and CCR5 activates AKT/GSK3 signaling resulting in upregulation of glycolysis in glioma cells." (PMID 30200472, 2018). "In vitro, flow-stimulated invasion was mitigated by both blocking the receptor CXCR4 as well as saturating the ligand CXCL12, suggesting this chemokine-receptor pathway plays a key role in glioma cell flow response." (PMID 30451884, 2018). "The novel CXCR4 antagonist showing good brain penetration was demonstrated to reduce growth in vitro and in vivo of GBM cells and induce glioma stem cell differentiation." (PMID 28057017, 2017). "By analyzing clinical specimens, we observed the co-localization of MIF, C-X-C motif chemokine receptor 4 (CXCR4) and VM in hypoxic regions of gliomas." (PMID 29113309, 2017). "A key message of the present study is that inhibition of PC-PLC by D609 also downmodulates CXCR4, EGFR expression and downstream signaling pathways responsible for cell growth and cell motility in our experimental glioma cells." (PMID 28423060, 2017). "Immunochemical studies of specimens of glioma patients revealed that hypoxia-induced overexpression of MIF and CXCR4 co-localized with VM." (PMID 29113309, 2017). "The top 5 pathways include genes involving GM-CSF Signaling, Protein ubiquitination pathway, glioma signaling, FAK Signaling and CXCR4 Signaling." (PMID 28845464, 2017). "The CXCR4/CXCL12 axis is particularly active in pseudopalisading areas surrounding the necrotic foci and in invading glioma cells." (PMID 26880981, 2016). "Studies have shown that post irradiation treatment, CXCR4 expression on glioma cells, including GL26 cells is upregulated suggesting a role of CXCR4 in tumor survival and therapeutic resistance." (PMID 27863376, 2016). "As before we confirmed that mNS GSC have a higher expression level of the stem cell markers CXCR4, MELK, PTCH, CD44, CD133, MSl1 and CD90, while GL261 GDC expressed higher level of the differentiated glioma marker glial fibrillary acidic protein (GFAP)." (PMID 27073883, 2016). "In fact, CXCL12 can activate phosphoinositide 3-kinase (PI3K)/Akt, IP3, and mitogen activated protein kinase (MAPK) pathways via CXCR4 and PLC/MAPK pathway via CXCR7, increasing cell survival in gliomas." (PMID 26880981, 2016). "A role for CXCL12 modulation of CXCR4 and CXCR7 was identified for most of the brain tumors including gliomas, meningiomas and even pituitary adenomas that frequently overexpress these receptors." (PMID 24904289, 2014). "Currently, CXCR4 inhibitor, Plerixafor, in combination with an anti-VEGF antibody, bevacizumab, is under evaluation in a phase I study of recurrent high grade glioma patients (NCT01339039)." (PMID 24971349, 2014). "CXCR4 activation in GBM CSCs, in combination with VEGF and HGF signaling pathways under hypoxia, is a key factor in determining NSC tropism toward gliomas." (PMID 24904289, 2014). "The expression of CXCR4 and CXCR7 in glioma cell lines were documented previously and CXCR7 is up-regulated in high grade gliomas." (PMID 23555768, 2013). "We then immunoprecipitated CXCR4-HA or empty vector from LN229 and LN308 glioma cells and analyzed it for co-precipitated CXCR7 using Western blotting." (PMID 23865743, 2013).
glioma (continued). "CXCR4 has been shown to be increased in CD133+ glioma stem cells, while CXCR7 marks the bulk population of glioma cells." (PMID 23555768, 2013). "Analysis of immunoprecipitated CXCR4 from LN229 and LN308 glioma cells revealed co-precipitated CXCR7." (PMID 23865743, 2013). "Since our observations so far suggested a functional interaction between CXCR4 and CXCR7, we investigated the potential binding of the two receptors in glioma cells." (PMID 23865743, 2013). "In the context of glioma, CXCR4 is elevated in GBM and grade III gliomas compared with grade II gliomas." (PMID 23555768, 2013). "It should also be noted that LN229 glioma cells migrated towards SDF-1α only in hypoxic conditions, where levels of CXCR4 and CXCR7 were higher." (PMID 23865743, 2013). "DSP1–7 was stably expressed in the glioma-derived NP-2 cell lines, which expressed CD4/CXCR4 (N4X4) or CD4/CCR5 (N4R5), respectively." (PMID 24050252, 2013). "Collectively, our findings indicate that both CXCR4 and CXCR7 mediate glioma cell migration towards SDF-1α in hypoxic conditions." (PMID 23865743, 2013). "Our results demonstrate that MMP-2-depleted-CM abrogated IR-induced SDF-1/CXCR4 expression and PI3/AKT-mediated angiogenesis in glioma xenograft cells." (PMID 23381805, 2013). "Taken together, our findings indicate that both CXCR4 and CXCR7 mediate glioma cell migration towards SDF-1α in hypoxic conditions." (PMID 23865743, 2013). "Taken together, our findings indicate that both CXCR4 and CXCR7 mediate glioma cell migration towards SDF-1α in hypoxic conditions and support the development of therapeutic agents targeting these receptors." (PMID 23865743, 2013). "We analyzed gliomas for expression of CXCL12 and CXCR4 and found abundant expression of CXCL12 in both Ntv-a- and Gtv-a Arf−/− gliomas and there was also a clear expression of CXCR4 in the same samples." (PMID 21949886, 2011). "Similar to mouse gliomas, MCs in the human gliomas showed a predominantly perivascular localization and stained positive for both CXCL12 and CXCR4." (PMID 21949886, 2011). "This suggests that glioma cells, in accordance with the results from the MC migration assay, are the primary source of CXCL12 production and hence attract MCs via a CXCL12/CXCR4 axis." (PMID 21949886, 2011). "After adding the CXCR4 agonist CXCL12, glioma cell lines were prevented from apoptosis and showed increased chemotaxis." (PMID 18781150, 2008). "Furthermore, we investigated the correlation between IGFBP5 expression and PD-L1, CXCR4 expression in glioma using the CGGA and TCGA databases and the results showed IGFBP5 expression was positively correlated with PD-L1 and CXCR4 expression." (PMID 38164271, 2024). "The C-X-C Motif Chemokine Receptor 4 (CXCR4), the receptor for SDF-1, which promotes EMT in several cancers, has been shown to increase the expression of MES genes in glioma cell lines and its higher expression correlates with significantly reduced survival in GBM." (PMID 38391963, 2024). "Since CXCR4 is the corresponding receptor for the cytokine CXCL12 expressed by glioma tumor cells, it is suggested that mast cells may be attracted to the tumor via the CXCL12/CXCR4 axis." (PMID 38275375, 2023). "Glioma cells also release CXCL12 and overexpress its receptor CXCR4." (PMID 38293652, 2023). "CXCR4 and CXCR7 are highly expressed on the surface of both microglia and glioma cells." (PMID 37153567, 2023). "Furthermore, it has been suggested that CXCR4 is a strong predictor of poor prognosis in GBM patients and a clinical prognostic factor in glioma patients." (PMID 37626511, 2023). "Importantly, we found a positive correlation between A3C and glioma stem cell marker genes such as CD133, SOX2, Notch3, CD44, and CXCR4 was noted." (PMID 37809064, 2023).
glioma (continued). "The activation of CXCR4 by CXCL12 induces migration and/or survival of neoplastic cells, such as tumor cells from brain tumors (neuronal and glial tumors), colorectal cancers, prostate cancer, melanoma, renal cell cancer, neuroblastoma cells, and ovarian cancer." (PMID 39355049, 2023). "In addition, CXCL16 as a chemokine as well as CXCR4 and CCR5 as chemokine receptors were identified in our study as possible vital immunomodulatory factors in glioma." (PMID 35896732, 2022). "Given that, we hypothesized that NK CD56bright, Tfh, and macrophage cell types might be closely related to immune regulation in TME of glioma, and B7H3, PDCD1, LAG3 and CXCL16, CXCR4, CCR5 might be key targets for glioma immunotherapy." (PMID 35896732, 2022). "In the TCGA database, co-expression analysis of hub genes with chemokines and related receptors also showed a regular pattern, with CXCL16 as a chemokine as well as CXCR4 and CCR5 as receptors negatively correlated (all P < 0.05, r < − 0.3) with all hub genes in glioma." (PMID 35896732, 2022). "Then, we analyzed CXCR4 expression in NHA and other glioma cell lines by qPCR." (PMID 35059468, 2022). "Importantly, Gαi-coupled GPCRs, including cannabinoid receptors 46, CXCR4 47, 48, dopamine D2 receptors 24 and melatonin receptor II (MTII) 49, were reported to be important for glioma progression." (PMID 34373757, 2021). "In this study, CCL2, CCL5, CXCR4, MMP9, and CXCR2 expression was found to be high in TERTmut glioma from all samples and IDHwt subgroups with high levels of neutrophil infiltration, which indicated that N2 phenotype neutrophils were associated with TERT mutation." (PMID 33996815, 2021). "Moreover, exposure to hypoxia produced a significant expression of CXCR4 and HIF-1α in glioma cells, while VEGF stimulated angiogenic response of CXCR4 in normal endothelial cells from brain microvessels." (PMID 34200145, 2021). "For both GBM and glioma, CXCL12 functions under hypoxic conditions in the CSC niche through an autocrine positive feedback loop that promotes cell survival, tumor progression, and cell proliferation, which can be inhibited by blocking CXCR4." (PMID 33530455, 2021). "CXCR4 and CXCL12 are the potent regulators of glioma stem cell proliferation." (PMID 32456359, 2020). "Our data suggested that FTY720 can block the cross-talk between glioma and GAMs by increasing microglial CXCR4 internalization rather than by affecting CXCL12 secretion by glioma." (PMID 32194542, 2020). "Glioma biopsies have increased expression in HIF-1α, MIF, and CXCR4." (PMID 31993365, 2019). "In U87 and U251 glioma cell lines, high expression of MIF and CXCR4 promoted EMT and VM formation." (PMID 31993365, 2019). "Based on these reports, we assume that the gp120-induced activation of glycolysis and cell proliferation might result from activation of cell surface signaling molecules, such as CXCR4 or CCR5 and further-downstream signaling activation in glioma cells." (PMID 30200472, 2018). "It was postulated that this effect was due to increases in both CXCR4 and CXCL12 in glioma cells." (PMID 30451884, 2018). "However, miR-126 worked as a tumor suppressor through inhibiting the target gene expression such as VEGF, CXCR4, DNMT1, KRAS in many cancers, especially glioma." (PMID 30233327, 2018). "In addition, CXCL12 and its receptors CXCR4/CXCR7 function by maintaining GBM stem-like cell survival and increasing glioma cell invasion." (PMID 28380429, 2017). "Another study reported a direct tropic interaction of human glioma U87-Luc cells with CXCL12-expressing endothelial cells which was blocked by CXCR4 antagonists but not CXCR7 antagonists." (PMID 27863376, 2016). "Thus, the inhibition of CXCR4 (and its interaction with CXCL12) is a potential target for inhibiting glioma cell invasion and recurrence." (PMID 27863376, 2016).
glioma (continued). "Moreover, we present evidence suggesting that tumor-associated vessels produce SCF that drives MC proliferation and that MC chemotaxis in gliomas involves interaction between CXCL12 and CXCR4." (PMID 21949886, 2011). "Taking into account that the CXCL12/CXCR4 interaction has a pronounced role in development of tumor vasculature, and that CXCL12 is a known MC chemotaxin, we demonstrated that both mouse and human gliomas were highly positive for CXCL12." (PMID 21949886, 2011). "Hence, we propose that the MC accumulation within the gliomas is, at least partly, explained by a glioma-driven expression of CXCL12, combined with strong expression of CXCR4 within the brain tumor MC population." (PMID 21949886, 2011). "Overexpression of CCR2, CCR4, CXCR1/2, and CXCR4 reportedly improved CAR T cell trafficking to brain tumors in preclinical studies.CAR T cell pretreatment with metformin/rapamycin also enhanced mitochondrial respiration, leading to improved CAR T cell efficacy in glioma." (PMID 40895575, 2025). "Previous studies have reported on the anti-glioma activities of CX and its constituents, including tetramethylpyrazine, ligustilide, and ferulic acid, which inhibit proliferation, invasion, and sensitize GBM to temozolomide via CXCR4, Rho GTPases, and PI3K/Akt pathways." (PMID 41155666, 2025). "In glioma-derived EVs from the cell line U251, several pro-angiogenic factors were identified, including the vascular endothelial growth factor (VEGF), the C-X-C chemokine receptor type 4 (CXCR4), the transforming growth factor b type 1 (TGF-b1), and matrix metalloproteinases (MMPs)." (PMID 40926108, 2025). "Notably, none of any studies were relevant with circRNA-induced CXCR4 regulation in glioma, even with the nonnegligible CXCR4 function in glioma." (PMID 35059468, 2022). "While CXCR4 and CXCR7 receptors are moderately expressed on normal endothelial cells, CXCR7 expression on these cells inside of the TME is significantly increased, and it has recently been proposed as a biomarker of tumor vasculature in cancers, like renal carcinoma and gliomas." (PMID 35269652, 2022). "In addition, the use of siRNAs and the chemical antagonist CCX771 have been explored to target CXCR7 in gliomas, inhibiting the phosphorylation of ERK1/2 and obtaining similar results as when targeting CXCR4, although further research needs to be performed regarding CXCR7 inhibitors." (PMID 33530455, 2021). "However, CXCR4 and ACKR3 expression is not specific to glioma-associated endothelial cells, and both receptors are also detected in endothelial cells from the developing brain or from the adult brain." (PMID 35008294, 2021). "In detail, the suppression of the stem-cell-like signature induced by the miR-302-367 cluster in glioma-initiating cells is mediated by the drastic downregulation of the pathway mediated by the chemokine receptor CXCR4 and its ligand SDF1, because miR-302a binds to the CXCR4 3′-UTR." (PMID 34439740, 2021). "[68Ga]Pentixafor was shown to have variable uptake characteristics in gliomas, the tumor SUVs were less than those of 18F-FET (although brain background was very low), and there was an inconsistent relationship between [68Ga]Pentixafor uptake and CXCR4 immunohistochemistry on resected tumor tissue." (PMID 32239371, 2020). "Moreover, those GSCs express not only a SDF-1/CXCR4 axis but also osteopontin (OPN) and cathepsin K (CTSK), showing how the niche that surrounds arterioles resembles bone marrow hematopoietic stem cell (HSC) niche proteins and recruits glioma stem cells by promotion of migration via CD44 and CXCR4." (PMID 33322379, 2020). "Autophagy has been variously proposed to promote or prevent cancer cell growth and invasion, and this may be related to activation or repression of metastatic programs controlled, at least in part and in several tumors including glioma, by the SDF-1/CXCR4 pathway." (PMID 31007847, 2019).
glioma (continued). "Although AMD3465 is another drug which is more specific than AMD3100 and has been shown to have anti-glioma effect in various models, to rule out any unreported off target effects of both these drugs, we chose to selectively knock down CXCR4 expression using shRNA." (PMID 27863376, 2016). "It is interesting that while both CXCR4 and CXCR7 are required for SDF-1α-induced migration of hypoxic glioma cells, blocking both CXCR4 and CXCR7 does not provide an additive effect, either with regards to migration assays or phosphorylation of ERK1/2 and Akt." (PMID 23865743, 2013). "Further, glioma cells expressed the MC chemotaxin CXCL12 and MCs expressed the corresponding receptor, i.e. CXCR4, suggesting that MCs could be attracted to the tumor through the CXCL12/CXCR4 axis." (PMID 21949886, 2011). "FTY720 could inhibit the growth, migration, and invasion of glioma by targeting GAMs to impede their effect on glioma cells, while also potentially blocking the chemoattraction of GAMs by inhibiting the MAPK-mediated secretion of IL-6 through the increased internalization of CXCR4." (PMID 34071306, 2021). "In addition, C–X–C motif chemokine receptor 4 (CXCR4), C–X–C motif ligand 3 (CXCL3), and matrix metallopeptidase 7 (MMP7), also considered as positively correlated genes, were reported as oncogenic genes and facilitate growth, invasion, migration, and chemoresistance in gliomas." (PMID 34868960, 2021). "Moreover, CXCR4 is also up-regulated by signaling pathways induced by non-tumor immune or inflammatory cells surrounding gliomas, which may mislead the interpretation of its clinical significance." (PMID 30082913, 2019). "However, unexpectedly, we observed that if MLV-B cores are pseudotyped with either the MCN or MCR HIV-2 Envs they both result in a restricted phenotype in HeLa/CD4 cells, but not in the NP2/CD4/CXCR4 (a permissive glioma cell line stably transduced with the HIV receptors) cells." (PMID 20929586, 2010). "Interestingly, our results presented that double-targeted knockdown of miR-21 and CXCR4 powerfully suppressed PI3K/AKT and Raf/MEK/ERK activation, which might have significant therapeutic values and offer some insights for further investigation of the molecular mechanism in glioma pathology." (PMID 33123586, 2020). "Currently, the correlation between CXCR4/CXCR7 expression and IDH1 has been reported in human glioma but has not been reported in AML yet." (PMID 33381455, 2020). "Current evidence suggests that most, if not all, GBMs express CXCR4 and CCR5 and these receptors are related to the survival, invasiveness, proliferation and resistance to the radio- and chemotherapy of glioma tumors." (PMID 30200472, 2018). "Glioma cell lines did not express CXCR3, CXCR4, CXCR6, CX3CR1, but high levels of CXCR7, which is a receptor for CXCL11 and CXCL12 and can mediate G-protein independent signals via arrestin." (PMID 26796342, 2016). "Inhibiting CXCR4 in LN229 and LN308 glioma cells that were knocked down for CXCR7 did not further reduce migration towards SDF-1α in hypoxic conditions and did not affect the levels of phosphorylated ERK1/2 and Akt." (PMID 23865743, 2013). "The correlation between CXCR4 mRNA expression and WHO glioma grade was determined with the use of GEO dataset GSE16011 (N = 284), and showed a relatively higher expression in high grade gliomas, whereas normal brain tissue was CXCR4 mRNA negative." (PMID 33550492, 2022). "The validation outcomes of CXCL16, CXCR4 and CCR5 in the CGGA database exhibited consistent negative correlation trends, suggesting that CXCL16, CXCR4 and CCR5 might act as potentially vital chemokine elements in glioma." (PMID 35896732, 2022). "The ELISA results showed that FTY720 did not affect CXCL12 secretion by glioma cells, indicating that FTY720 could regulate CXCL12–CXCR4 cross-talk between microglia and glioma via decreasing the expressions of CXCR4 on the microglia." (PMID 32194542, 2020).